CD47 (CD47 molecule)
Diseases named in the same sentence as CD47 in open-access papers (continued):
Sharing a sentence is not in itself a finding about the gene and the disease.
tumor (continued). "Several immune checkpoint genes (HAVCR2, CD47, LGALS9, and CD276) were gradually upregulated along the DC differentiation trajectory, especially at the late stage, revealing that C3-DC might suppress tumor immunity." (PMID 36788228, 2023). "Checkpoint inhibitors can hinder CD47’s interaction with checkpoint receptors like programmed death-1 (PD-1) and T-cell immunoglobulin and mucin-domain containing-3 (TIM-3), bolstering anti-tumor immunity and potentially enhancing clinical outcomes in cancer patients." (PMID 38188674, 2023). "This leads to a debate about CD47-SIRPα blocking agents that whether blocking the interaction between SIRPα and CD47 alone, independent of FcR activation, is sufficient to trigger macrophage phagocytosis and tumor cell elimination." (PMID 37691932, 2023). "Although a few studies have shown that an anti-CD47 antibody monotherapy was able to inhibit tumor growth in some syngeneic mouse models, most studies in syngeneic mouse models and in clinical trials reported that anti-CD47 antibody alone did not exert significant antitumor effects." (PMID 36650558, 2023). "The phagocytosed number of 4T1 tumor cells by 100 macrophages was quantified in vitro, and equivalent phagocytose (>100 4T1 cells) was induced by anti‐CD47‐PCM@NP compared with direct treatment of anti‐CD47, in contrast to the single‐digit uptake in the PCM@NP group." (PMID 36683161, 2023). "Thus, CD47 is regarded as a ‘do not eat me’ signal sent by tumor cells to macrophages to avoid being phagocytosed." (PMID 37108657, 2023). "In subcutaneous and orthotopic transplantation mouse tumour models, the STAT3 inhibitor napabucasin prevented tumour growth and induced the expression of calreticulin and the protein disulfide isomerase family A member 3 (PDIA3; also known as ERp57) but suppressed that of CD47 and GLUT1." (PMID 35665592, 2022). "Whether DC killing of tumor cells mediated by NI-1701 depends primarily on the blockade of the CD47/SIRPα axis or on Fc-dependent mechanisms has not been elucidated yet and remains to be clarified." (PMID 35538512, 2022). "Interestingly, AO176 blocked the CD47/SIRPα interaction to stimulate phagocytosis of tumor cells, and also directly killed tumor cells (non-ADCC)." (PMID 35418166, 2022). "Mechanistic studies on tumor-infiltrating immune cells and cytokines/chemokines showed that ZL-1201 neutralizes CD47–SIRPα antiphagocytic signaling, and combination with Fc-intact mAbs further provide a prophagocytic signal to maximally induce potent ADCP and promote tumor clearance." (PMID 36970051, 2022). "CD47- SIRPα interaction leads to recruitment of downstream Src homology-2 domain-containing protein tyrosine phosphatases (SHP-1 and SHP-2), preventing the accumulation of myosin-IIA at the phagocytic synapse, thereby inhibiting macrophage-mediated tumor phagocytosis." (PMID 35883692, 2022). "Notably, a greater signal at the tumor site was seen with 7DC2-DyLight680 compared to 7DC4-DyLight680, further suggesting that 7DC2-VCMMAE is more stable and specific than 7DC4-VCMMAE in targeting CD47-expressing tumor tissues in mice." (PMID 35646646, 2022). "Finally, we will discuss the anti-PD-L1 and anti-CD47 antibodies, which are not tumor-expressed ligands of immune checkpoints, and which mandate a different reasoning from that underlying the targeting of checkpoints expressed on immune cells." (PMID 36142278, 2022). "CD47 signaling regulates the VEGF immunosuppressive activity by interacting with VEGF receptor-2.Therefore, hypoxia directly suppresses the antitumor immune response, further enabling immune escape, as well as induces tumor cells to release immunosuppressive molecules." (PMID 35659268, 2022). "In addition to the suppressive role of CD47 and SIRP-alpha interaction in tumor cell phagocytosis, CD47 and SIRP-alpha interaction can promote trafficking of SIRP-alpha+CD103(-) dendritic cells into mediastinal and mesenteric lymph nodes and driving Th17 and Th2-biased responses." (PMID 35634325, 2022).
tumor (continued). "Similarly, miR-200a promotes phagocytosis of tumor cells by macrophages by targeting CD47, a “do not eat me” signal protein overexpressed in tumor cells." (PMID 36158660, 2022). "All the data suggested that the effect of PQ912 might be ascribed to the regulation of CD47 expression on the tumor cell surface rather than directly killing tumor cells." (PMID 35832081, 2022). "We found that neither anti-CD47 antibodies nor MNA had single-agent activity in this tumor model." (PMID 36223740, 2022). "However, it appears that neutrophils are less capable of killing hematologic cancer cells, and blockade of the CD47-SIRPα axis with anti-CD47 mAbs is not enough to promote tumor elimination." (PMID 35884427, 2022). "The therapeutic use of CD47 blockade combined with either temozolomide or irradiation enhanced its effects by increasing macrophage-mediated phagocytosis of GBM cells, resulting in an increased survival rate of GBM-implanted mice and a significant inhibition of tumor growth." (PMID 35054787, 2022). "Additionally, for the antagonism of CD47, a “Not Eat Me” signal is overexpressed on the surface of most tumours by a signal-regulatory protein alpha." (PMID 36298556, 2022). "Two other enhancers, E5 at a downstream CD47 gene-associated super enhancer and E3.2 within an upstream CD47 gene-associated super enhancer, were discovered in some but not all cancer cell lines, indicating that CD47 regulation may be tumor specific." (PMID 35865547, 2022). "RRx-001, inhibiting CD47 transcription, exhibits no obvious hematologic or systemic toxicity in clinic, suggesting that downregulating tumor CD47 expression by using small-molecule inhibitors may avoid hematological side effects." (PMID 36274066, 2022). "Thus, in patients with normal or high MHCI expression in tumor cells, drugs targeting the MHCI/LILRB1 axis may facilitate antitumor immune responses and act synergistically with drugs targeting the CD47/SIRPα axis." (PMID 35892835, 2022). "Importantly, healthy cells are not killed by T cells after CD47 blockade, which suggests that additional microenvironmental cues allow macrophages to distinguish between tumor and healthy cells." (PMID 35565443, 2022). "In the treatment groups, rat anti-mouse CD47 antibody generated from MIAP301 hybridoma cells (16 mg/kg), ET (30 mg/kg), or combination, was administrated via i.p. every other day for 14 days (total seven treatments) till Day 38 and tumor imaging and animal survival were monitored." (PMID 35314680, 2022). "After dividing our patients into a low-grade and a high-grade subgroup, we did not observe significant changes in the proportions of CD47+ tumor cells between these groups, nor in the two different tissue compartments (tumor center, tumor periphery) within the same subgroup." (PMID 36171566, 2022). "Indeed, SIRPα/CD47 pathway is referred to as the “do-not-eat-me” signal and tumor cells with CD47 expression can be recognized as self-normal cells and escape phagocytosis." (PMID 35493456, 2022). "With similar reasoning, the tumor binding antibody in tumors with dual inhibition could not be enhanced to the level of anti-CD47 treatment, suggesting an increased tumor cell death synergistically induced by blocking FAO and CD47." (PMID 35314680, 2022). "Moreover, the blocking interaction of CD47 and SIRPα was also demonstrated to reprogram MDSC and tumor-associated macrophages (TAMs) as non-suppressive." (PMID 35746616, 2022). "However, necrosis of tumor cells is usually considered to be immunologically harmful since they expose the CD47 on the surface that induce negative engulfment “do not eat-me” signals 9,10." (PMID 36258234, 2022). "GPNMB triggers the self-renewal of spheroids to increase cell survival and the tumor-forming ability of macrophages interacting with tumor cells, and GPNMB activates the expression of the IL-33cytokine and its receptor, IL-1R1L, through CD47 and is sufficient to induce tumor spheroid formation." (PMID 35678671, 2022).
tumor (continued). "CD47 blockade alone is not sufficient to trigger macrophage anti-tumor activity." (PMID 34717705, 2021). "Besides, the binding of CD47 on cancer cells with the inhibitory receptor signal regulatory protein alpha (SIRPα) on TAM suppresses the ability of macrophages to detect and phagocytose tumor cells." (PMID 33947438, 2021). "Interestingly, MYC has been shown to regulate the anti-tumor immune response in murine models of T cell acute lymphoblastic leukemia (ALL) and liver cancer by inducing the expression of CD47 and/or PD-L1 immune checkpoint molecules and recruiting TAMs, while excluding T cells among other mechanisms." (PMID 33842331, 2021). "Since CD47 is the “do not eat me” signal for macrophages, this effect could promote the innate anti-tumor immunity." (PMID 34943954, 2021). "Among various pathophysiologic mechanisms fostering immune evasive tumor behavior, cluster of differentiation 47 (CD47), a transmembrane molecule commonly present on non-malignant hematologic cells, including red blood cells and thrombocytes, has emerged as a promising target." (PMID 34944850, 2021). "Pioneering studies identified B6H12, a function-blocking anti-CD47 monoclonal antibody (mAb) that can inhibit the binding of two endogenous partners, SIRPα and the secreted glycoprotein Thrombospondin-1 (Tsp-1); B6H12 showed efficacy in pre-clinical tumor models and hematological malignancies." (PMID 34471125, 2021). "For example, CD47 could also interact with thrombospondin-1 (TSP-1), which is an extracellular ligand secreted by vascular and inflammatory cells; TSP-1 regulates cell motility, proliferation, and differentiation of some tumor cell lines in vitro." (PMID 34195295, 2021). "Thus, the induction of CD47 in hypoxic tumor cells leads to a disruption of macrophage signaling and does not allow phagocytosis of tumor cells." (PMID 34595122, 2021). "Targeting TAM inhibitory (“do not eat”) signals-CD47/SIRPα axis by therapeutic SIRPα antibodies could inhibit tumor formation inAOM-DSS-induced CRC." (PMID 34667145, 2021). "Indeed, CD47 blockade using monoclonal antibodies facilitates the clearance of PDAC cells via macrophage-dependent phagocytosis in in vitro engulfment assays, and decreases metastatic tumor burden and improves survival in mice." (PMID 34201127, 2021). "Since PD-L1 is expressed in tumor cells, IBI322 can selectively bind to tumor cells more effectively than anti-CD47 monospecific antibody, thus reducing the possibility of binding to CD47 expressed on RBCs, which could ultimately reduce the toxicity associated with anti-CD47 antibodies." (PMID 34305918, 2021). "In addition, the co-targeting of CD47 and CD19 enhances the expected safety, as well as induces antibody dependent cytotoxicity (ADCC) by retaining the function of its IgG1 Fc region, thereby providing a second mechanism for anti-tumor activity." (PMID 34305918, 2021). "It remains to be uncovered how exposure to elevated and non-oscillatory CD47 and PD-L1 may affect the molecular clock and downstream functions of tumor-infiltrating immune cells." (PMID 34299381, 2021). "Thus, MNPs have proven useful for enhancing the macrophage anti-tumor activity, both in inducing the M1 re-polarization of TAMs and as carriers of inhibitors on tumor CD47 “do-not-eat-me” signal." (PMID 34675914, 2021). "Tumor escape from immune surveillance is further promoted by the expression of the “do not eat me” signal, CD47 and the increased expression of programmed cell death protein-1 (PD1) by tumor-infiltrating T-cells and of its ligand PD-L1 (programmed death-ligand 1) by TAMs." (PMID 34771453, 2021). "The function of the cell membrane varies by cell type; for example, red blood cells (RBCs) evade the immune system due to the expression of CD47 on the membrane but have no targeting ability, whereas white cell membranes display the characteristic of tumor homing." (PMID 34142930, 2021).
tumor (continued). "CD47 expression was positively correlated with CD8+ T cell infiltration (r=0.102, p=2.48e-02), CD4+ T cell (r=0.107, p=1.90e-02), Neutrophil (r=0.246, p=4.50e-08) and dendritic cell (r=0.162, p=3.71e-04), negatively correlated with tumor purity (r=-0.17, p=1.73e-04)." (PMID 34966389, 2021). "Nevertheless, CD47-SIRPα may not be the only mechanism by which tumor cells can evade neutrophil-mediated immune destruction as neutrophils are endowed with other potent inhibitory receptors." (PMID 34503071, 2021). "It combines with CD47 expressed on tumor cells to send a "do not eat me" signal to macrophages." (PMID 34717705, 2021). "Indeed, a selective targeting of TSP-1 is expected to promote an overall anti-tumor immune response, without interfering with physiological functions of CD47." (PMID 34638503, 2021). "The SαV-C-NVs and CD47 mAbs showed limited therapeutic effects on antitumor recurrence; in contrast, after they were integrated with P-NVs and M1-NVs, the resulting hNVs significantly reduced tumor recurrence as four out of six mice had no detectable tumor." (PMID 32999291, 2020). "Three different human tumor cell lines of MCF7, HT29 and Jurkat were offered to macrophages as target cells, and the results showed that pep-20 significantly increased macrophages-mediated phagocytosis of tumor cells, which was slightly inferior to the anti-CD47 antibody (B6H12) positive control." (PMID 33020240, 2020). "Furthermore, combination therapies were developed to achieve increased tumor specificity and decreased toxicity to CD47-expressing non-malignant cells." (PMID 32677994, 2020). "Cancer cells with HER2-promoted proliferation may be equipped with an additional survival advantage due to CD47-mediated anti-phagocytosis and vice versa, leading to an immunosuppressive tumor microenvironment and a lack of treatment response." (PMID 32929084, 2020). "However, tumor growth was significantly delayed in mice vaccinated with anti-CD47 Ab-coated B16F10 cells (without anti-PD-1 antibody) compared to anti-PD-1 antibody-treated mice." (PMID 31996683, 2020). "Thus, for the treatment of recurrent tumors expressing HER2, a dual blockage of CD47 and HER2 may lead to the synergetic tumor inhibition by radiotherapy." (PMID 32929084, 2020). "However, in vitro killing of the tumor cells by NK cells was not inhibited by the same antibody, suggesting CD47 function in NK cells to be independent of SIRPα." (PMID 32117298, 2020). "Additionally, selectively decreased CD47 expression induced by radiation of HPV-positive tumor cells in combination with cisplatin treatment efficiently improved immune-mediated tumor clearance in vivo in immunocompetent but not immunodeficient Rag1 mice." (PMID 32005919, 2020). "TSP-1 binding to CD47 activates vascular growth factor (VEGF) and its receptor (VEGFR2) to regulate angiogenesis while CD47 binding to integrin αVβ3 promotes neovascularization that facilitates plaque formation, tumor cell growth, and the spread of inflammation." (PMID 32733941, 2020). "CD47 blockade may also enhance tumor radiosensitivity via improved CD8 T cell immunosurveillance in syngeneic mouse models, STING-based tumor visibility, and selective upregulation of protective pathways against oxidative stress and upregulation of DNA repair in normal tissues." (PMID 35582455, 2020). "Therefore, miR-128 regulated the infiltration of anti-tumor immune cells, including DCs, CD8+ T cells, and NKT cells, in the immune microenvironment through the ZEB1/CD47 axis, accompanied by the inhibition of the EMT process through ZEB1, ultimately inhibiting tumor growth and metastasis." (PMID 32536914, 2020). "Blocking CD47 on tumor cells will block “do-not-eat-me” signals." (PMID 32161718, 2020). "Similarly, IMM0306, a CD20 x CD47 BsAb developed by ImmuneOnco has achieved remarkable therapeutic effects in various tumor models and showed no binding to human erythrocytes in pre-clinical study." (PMID 32989604, 2020).
tumor (continued). "Combination targeting of both CD47 and PD-L1 resulted in synergistic inhibitory effect on tumor growth in the MPC-83 but not Panc02 syngeneic PDAC mouse model due to their differential effect on the key immune-activating genes and infiltrating immune cells in the TME." (PMID 31771616, 2019). "Thus, mutations in components of the WNT/β-catenin signaling pathway induce aberrant MYC expression and, because of that, increased expression of the immune checkpoint proteins PD-L1 and CD47 and a non-T cell-inflamed tumor phenotype." (PMID 31921125, 2019). "However, CD47 is a widely expressed counter-receptor for the inhibitory phagocyte receptor SIRP in the tumor microenvironment, which limits cooperation between anti-tumor T cell immunity and radiation therapy, as its blocking enhances tumor radio-sensitivity." (PMID 31661894, 2019). "Our research provided evidence that CD47 blockade could sensitize NSCLC to anti-angiogenic therapy and potentiate its anti-tumor effects by enhancing macrophage infiltration and tumor cell destruction, providing novel therapeutics for NSCLC by disrupting CD47/SIRPα interaction and angiogenetic axis." (PMID 31829270, 2019). "Upon confirming the immune response to CD47−/− cancer cells, we next sought to determine whether γ-irradiate, non-replicating CD47−/− cancer cells can be used as a vaccine to suppress tumor growth and reduce tumor progression." (PMID 31882679, 2019). "However, in NCG mouse models using the same human tumor implantation, treatment with anti-CD47 did not reduce tumor growth." (PMID 31771616, 2019). "Therefore, a CD47-targeting therapeutic has strong potential for treatment of a broad range of tumor types through multiple immune- and non-immune-mediated mechanisms." (PMID 31276567, 2019). "Importantly, the lack of signal on CD45− tumor cells upon CD47 staining using the same mAb clone as for treatment indicated that the CD47 blockade was effective in vivo." (PMID 30938231, 2019). "It is not known if ferumoxytol-MRI can monitor tumor response to CD47 mAb therapy." (PMID 30674867, 2019). "Since CD47 mAbs activate TAM phagocytosis in tumors, we hypothesized that successful CD47 mAb therapy would increase ferumoxytol nanoparticle retention and T2-signal enhancement of the tumor tissue." (PMID 30674867, 2019). "For example, inhibition of the “do not eat-me” CD47-SIRPα interaction between tumor cells and phagocytic macrophages leads to an anti-tumor immune response characterized by the presence of CD8+ cytotoxic T lymphocytes and absence of FOXP3+ immunosuppressive T regulatory cells." (PMID 30187085, 2018). "Since CD47 is overexpressed on cancer cells with respect to normal cells, we propose that the SIRPα domain of the licMAB would not bind to normal cells expressing CD47 but facilitate the targeting of dual antigen-expressing tumor cells led by high affinity binding to CD33." (PMID 28061465, 2017). "However, targeting GRP78 increased CD47 and calreticulin levels in normal mammary gland tissue, unlike tumor tissue." (PMID 28815041, 2017). "In patient-derived xenograft models, CD47 targeting alone did not result in relevant slowing of tumor growth, but the addition of gemcitabine or Abraxane resulted in sustained tumor regression and prevention of disease relapse long after discontinuation of treatment." (PMID 29156578, 2017). "Furthermore, they imply that the endogenous low affinity extracellular domain of SIRPα does not function as a robust CD47-targeting agent by itself and that the activity of licMABs is dominated by high affinity binding to the tumor antigen." (PMID 28061465, 2017). "Taken together, the binding properties of licMABs enable these molecules to discriminate between CD33 negative and CD47 positive healthy cells, and CD33 and CD47 double positive tumor cells, and to selectively bind to the latter, avoiding undesired side effects." (PMID 28061465, 2017).